TMEM203 (transmembrane protein 203)
Description:
Involved in the regulation of cellular calcium homeotasis. Required for spermatogenesis. Acts as a regulator of STING-mediated inflammatory signaling in macrophages. Forms a complex with STING, promoting the activity of TBK1 kinase and the transcription factor IRF3, leading to activation of type I interferon expression (By similarity).
Synonyms: MGC14327; HBEBP1
Tractability: Antibody: UniProt predicts a signal peptide or a membrane-spanning region.
Gene: Protein-coding gene on chromosome 9 (137,204,082 to 137,205,648, reverse strand). Ensembl gene ENSG00000187713.
Subcellular location: Endoplasmic reticulum membrane; Endoplasmic reticulum-Golgi intermediate compartment; Lysosome membrane
Gene Ontology:
Molecular function: protein binding
Biological process: intracellular calcium ion homeostasis; spermatogenesis
Cellular component: endoplasmic reticulum; endoplasmic reticulum membrane; endoplasmic reticulum-Golgi intermediate compartment; lysosomal membrane
Genetic constraint (gnomAD): Loss-of-function variants: 4 observed, 7.51 expected, observed/expected ratio (o/e) 0.53, 90% interval 0.26 to 1.22. That is too few expected variants to judge how well the gene tolerates losing a copy. Missense variants: 127 observed, 181.7 expected, observed/expected ratio (o/e) 0.7, 90% interval 0.6 to 0.81. Synonymous variants: 92 observed, 85.56 expected, observed/expected ratio (o/e) 1.08, 90% interval 0.91 to 1.28.
Homologues: Orthologues: chimpanzee TMEM203 (100% identical), macaque TMEM203 (99% identical), dog TMEM203 (98% identical), guinea pig TMEM203 (98% identical), mouse Tmem203 (98% identical), pig TMEM203 (98% identical), rat Tmem203 (98% identical), tropical clawed frog tmem203 (82% identical), zebrafish tmem203 (79% identical), Drosophila melanogaster CG33932 (40% identical).
Diseases named in the same sentence as TMEM203 in open-access papers:
TMEM203 is named in the same sentence as 6 diseases in open-access papers, as found by Europe PMC text mining. Sharing a sentence is not in itself a finding about the gene and the disease. The quoted sentences say what the papers report.
Azoospermia (1 paper, 2015). Absence of any measurable level of sperm,whereby spermatozoa cannot be observed even after centrifugation of the semen pellet. "Histologic evaluation of the epididymides harvested from either 38-week-old or 48-week-old male Tmem203 deficient mice also showed a complete lack of mature spermatozoa in the epididymides (azoospermia) compared to wild type mice." (PMID 25996873, 2015).
fragile X syndrome (1 paper, 2016). A genetic syndrome caused by mutations in the FMR1 gene which is responsible for the expression of the fragile X mental retardation 1 protein. "This domain has been identified to be involved with the Fragile-X syndrome through the protein TMEM185A, however TMEM203 and TMEM60 share only ~10 % identity to the TMEM185A/B proteins and ~21 % identity between each other." (PMID 27030248, 2016).
Infertility (1 paper, 2015). "However, it is also possible that defects Sertoli and Lydig cells could also play some or a major role in the infertility in Tmem203 deficient mice." (PMID 25996873, 2015).
systemic lupus erythematosus (1 paper, 2019). An autoimmune multi-organ disease typically associated with vasculopathy and autoantibody production. "Unlike STING, TMEM203 mRNA levels are elevated in T cells from patients with systemic lupus erythematosus, a disease characterized by the overexpression of type I interferons." (PMID 31346090, 2019).
teratozoospermia (1 paper, 2015). "In addition, ultra-structural evaluation of the testes from Tmem203 null mice revealed abnormalities associated with the shape of the head of individual elongated spermatids (teratozoospermia) despite apparent normal condensation of chromatin and morphology of the acrosome." (PMID 25996873, 2015).
tumor (1 paper, 2022). "Since the HLA uLigand PTMEM203_B*07/C*16 (RSAGPRPAL) showed the highest frequency of tumor-specific presentation (8/45, 17.8%), we performed additional functional testing on the TMEM203 TLS." (PMID 35239002, 2022).